SIRT1 (sirtuin 1)
Diseases named in the same sentence as SIRT1 in open-access papers (continued):
Sharing a sentence is not in itself a finding about the gene and the disease.
breast cancer (continued). "The implications of SIRT1 in breast cancer occurrence and development have been reported and largely studied over recent years, but its exact role in breast cancer remains very controversial and paradoxical so far." (PMID 30380732, 2018). "Nonetheless, our findings emphasize the significance of protein subcellular distribution in cancer biology, diagnosis and targeted therapy, and explain the seeming discordance between SIRT1 and human breast cancer in the literature." (PMID 30038266, 2018). "SIRT1 knockdown has generated 2 distinct profiles of both epi-marks enrichment on targeted gene promoters that corresponds to the 2 main molecular breast cancer subtypes." (PMID 30093977, 2018). "In conclusion, we analyzed an aspect of SIRT1 epigenetic control in breast tumors and established SIRT1 status as an epigenetic eraser in breast cancer." (PMID 30093977, 2018). "These novel findings point to a potential use of SIRT1 as an epigenetic therapeutic target in breast cancer." (PMID 30093977, 2018). "The data evoke the possibility that SIRT1 plays a role in the epigenetic regulation of these genes expression in breast cancer." (PMID 30093977, 2018). "This is the first report that characterizes the epigenetic behavior of SIRT1 in breast cancer and establishes its status as an epigenetic eraser in human breast carcinoma." (PMID 30093977, 2018). "To clarify the role of SIRT1 in breast cancer cells, we perturbed SIRT1 levels in breast cancer cells." (PMID 29752439, 2018). "Given that PRRX1 deficiency promotes MET and CSCs in breast cancer, we reasoned that re-introduction of PRRX1 would reverse MET and CSC-like phenotypes in SIRT1-depleted cells." (PMID 30038266, 2018). "Combining SIRT1 inhibitors with 5-fluorouracil showed synergistic effects in inhibiting tumor growth and metastasis in breast cancer cells." (PMID 29520231, 2018). "The partial MET and cancer stemness induced by SIRT1 deficiency, and the correlation between SIRT1 and DMFS prompted us to investigate the function of SIRT1-PRRX1-KLF4 axis in breast cancer metastasis." (PMID 30038266, 2018). "To further elucidate SIRT1 epigenetic role in human breast cancer, we conducted direct H3k4ac and H3k9ac ChIP assays on transfected cell lines." (PMID 30093977, 2018). "Lastly, evidences on the ability of SIRT1 to interact with TGFß signaling, a concurrent pathway significantly involved in breast cancer progression, are reported." (PMID 30319540, 2018). "The contradictory functional roles of SIRT1 in breast cancer have been extensively studied over recent years." (PMID 30093977, 2018). "Loss of SIRT1 has been reported to cause hyper-acetylation of SMAD4 and promote breast cancer metastasis." (PMID 30001742, 2018). "Conflicting studies concerning SIRT1 ambiguous involvement in breast cancer extend to many aspects of the disease." (PMID 30380732, 2018). "SIRT1 depletion has led to increased H3k4 acetylation in 5 intrinsic subtype breast cancer cell lines, thus, the deacetylation of H3k4ac seems to be mainly dependent on SIRT1 histone deacetylase activity in breast cancer." (PMID 30093977, 2018). "In this study, we elucidated SIRT1 epigenetic role and analyzed the link between the latter and histones H3 and H4 epigenetic marks in all 5 molecular subtypes of breast cancer." (PMID 30093977, 2018). "We concluded that SIRT1 differential epigenetic regulation in breast cancer is predominantly governed by gene type and molecular subtype." (PMID 30380732, 2018). "The present report adds a layer of clarity on the ongoing controversy of SIRT1 behavior in human breast carcinoma." (PMID 30093977, 2018). "To address the confusion regarding SIRT1-dependent epigenetic regulation in BC pathogenesis, we characterized in recent studies an aspect of SIRT1 epigenetic behavior in human breast carcinoma." (PMID 30380732, 2018).
breast cancer (continued). "This highly context-specific role of SIRT1 in breast carcinoma seems to depend mainly on its upstream regulators or downstream substrates, as well as on its spatial distribution, cellular and molecular context, and tumor types." (PMID 30380732, 2018). "This dual expression pattern of SIRT1 in tumors points to a differential role of SIRT1 in human breast cancer." (PMID 29340027, 2017). "High expression of SIRT1 has been found in several cancers including, breast cancer, prostate cancer, lung cancer, colon cancer, and gastric cancer, which specific function is involved in cell proliferation, survival, differentiation and carcinogenesis." (PMID 28878214, 2017). "Here, we evaluated both the mRNA and protein expression patterns of SIRT1 using human breast tumors and their corresponding normal breast tissues, in all 5 molecular subtypes of breast cancer." (PMID 29340027, 2017). "Upregulation of SIRT1 in breast cancer cells is correlation to inactivation of tumor suppressor HIC1 (hypermethylated in cancer 1) by DNA hypermethylation." (PMID 28600541, 2017). "SIRT1 has been found to suppress epithelial-mesenchymal transition (EMT) in HMLER breast cancer cells; reduced SIRT1 expression increases metastasis in nude mice." (PMID 28600541, 2017). "In breast cancer cells, inhibition of SIRT1/2 decreased Frizzled7 (FZD7) protein expression, as well as β‐catenin and c‐Jun binding to the FZD7 promoter." (PMID 28994177, 2017). "Studies in breast cancer have confirmed that SIRT1 is involved in tumorigenesis, metastasis and chemoresistance." (PMID 29340027, 2017). "Several studies have investigated SIRT1 expression in breast cancer, but while some studies found upregulated SIRT1 expression, others did not concur." (PMID 29340027, 2017). "The results found here revealed different SIRT1 expression patterns among different breast cancer molecular subtypes." (PMID 29340027, 2017). "After classifying the breast tumors used in ascending order of aggressivity, decreased SIRT1 expression was found to correlate with increased breast cancer aggressivity and poor prognosis." (PMID 29340027, 2017). "Here, using a cohort of 50 human breast tumors and their matched normal tissues, we investigated SIRT1 expression levels in the 5 molecular subtypes of breast cancer according to the St Gallen classification (2013)." (PMID 29340027, 2017). "On the other hand, pharmacological Sirt1 inhibition by sirtinol exerts a broad anti-tumor effect on several cancers, such as melanoma, breast cancer, and prostate cancer." (PMID 29090089, 2017). "Sirt1 knockdown dramatically improved radiosensitivity of breast cancers by suppressing DNA damage repair." (PMID 28882183, 2017). "After statistical analysis, the results showed a dual expression profile of SIRT1 in human breast carcinoma, with significant overexpression in luminal and HER2-enriched subtypes and significantly reduced expression in the triple-negative subtype." (PMID 29340027, 2017). "Up-regulation of SIRT1 has been reported in various human malignancies including breast cancer, prostate cancer, lymphoma, colon cancer, gastric cancer and hepatocellular carcinoma." (PMID 26999517, 2016). "SIRT1 expression levels, in normal and breast tumour tissues from 28 patients with breast cancer, were evaluated to determine correlations with clinicopathological variables." (PMID 27793039, 2016). "In parallel, SIRT1 was shown to exert an essential role toward the oncogenic signaling mediated by the estrogen receptor-α (ERα) in breast cancer cells." (PMID 27916001, 2016). "SIRT1 inhibits breast cancer progression and accelerates the apoptosis of human breast cancer cell lines by downregulating the expression of pro-survival Bcl-2 protein." (PMID 26912776, 2016). "Their further analysis of 44 breast cancer and 263 hepatic carcinoma cases also revealed reduced expression of SIRT1 in these tumors." (PMID 26999517, 2016).
breast cancer (continued). "Serum SIRT1 level in breast cancer patients was significantly higher than that of normal subjects reaching a value that was almost 2-fold that of the normal control (p < 0.0001)." (PMID 26999517, 2016). "Hardy-Weinberg equilibrium for SIRT1 rs3758391, rs3740051 and rs12778366 in control subjects and breast cancer patients." (PMID 26999517, 2016). "Up-regulation of SIRT1 has been reported in various human malignancies including breast cancer, prostate cancer, acute myeloid leukemia, and primary colon cancer." (PMID 26999517, 2016). "Such suggestion is based on the previously reported correlation between SIRT1 expression and lymph node status in breast cancer." (PMID 26999517, 2016). "SIRT1 has been suggested to play a role in epigenetic silencing of DNA-hypermethylated tumor suppressor genes in breast cancer cells." (PMID 27528025, 2016). "Previous studies have explored the association of silent mating-type information regulator 2 homolog 1 (SIRT1) gene expression with prognosis in breast cancer." (PMID 26999517, 2016). "The present investigation revealed considerably higher serum SIRT1 levels in breast cancer patients than in normal subjects." (PMID 26999517, 2016). "Thirdly and most importantly, our observations of significantly higher serum levels of SIRT1 in breast cancer patients reveal a genotype-dependent pattern." (PMID 26999517, 2016). "Breast cancer patients exhibited elevated serum SIRT1 levels which varied among different tumor grades." (PMID 26999517, 2016). "who demonstrated that ER and PR expression significantly correlated with the overexpression of SIRT1 in breast cancer tissue." (PMID 26999517, 2016). "Then, we applied subcutaneously implanted tumor model in BALB/c mice to determine the effect of MSCs-Sirt1 on 4T1 breast cancer cells growth in vivo." (PMID 27782173, 2016). "TT genotype carriers had significantly higher serum SIRT1 levels compared to other rs3758391 genotypes in the breast cancer group (p = 0.005)." (PMID 26999517, 2016). "Previous work with these two compounds in combination on MDA-MB-157 and HCC1806 breast cancer cells have shown them to affect the activity of SIRT1; therefore, we investigated the effects of compounds on HDAC and HAT enzyme activities in the current study." (PMID 27159275, 2016). "Specifically, miR-34a directly down-regulates the expression of BCL-2 and SIRT1, inhibiting the proliferation and migration of breast cancer cells." (PMID 26423775, 2015). "SIRT1 localises to the promoter of sFRP2, directly contributing to the aberrant epigenetic silencing of breast cancer cells." (PMID 26568817, 2015). "We found that breast cancer cells treated with HNK exhibited an increase in the expression of SIRT1 and SIRT3 within 30 minutes post-treatment." (PMID 26359358, 2015). "SIRT1 can promote cell migration and metastasis by directly interacting and deacetylating cortactin in breast cancer." (PMID 26318035, 2015). "It was discovered that SIRT1 knockdown in human breast cancer cells resulted in a decrease in hTERT mRNA expression at the third day and enzyme activity at the fifth day of treatment as evidenced by RT-PCR and TRAP activity, respectively." (PMID 26459286, 2015). "For instance, in breast cancer cells SIRT1 was shown to exert an essential role toward the oncogenic signaling mediated by the estrogen receptor-α (ERα)." (PMID 26225773, 2015). "Our current results confirmed the inhibitory effects of miR-34a overexpression and SIRT1 knock-down in the proliferative potential of breast cancer cell line." (PMID 25826085, 2015). "For example, in breast cancer cell lines, SIRT1 has been shown to positively regulate the CYP19A1 gene, which encodes the aromatase protein." (PMID 25569080, 2015). "Here we found low levels of miR-34a and high levels of SIRT1 in CD44+/CD24− breast cancer stem cells (BCSCs)." (PMID 25826085, 2015).
breast cancer (continued). "Collectively, our data provide novel insights into the multifaceted action triggered by estrogenic GPER signaling, which engages also SIRT1, toward breast cancer progression." (PMID 26225773, 2015). "The expression of both DBC1 and SIRT1 predicted shorter survival of gastric carcinoma, breast carcinoma, clear cell renal cell carcinoma, soft-tissue sarcoma, and diffuse large B cell lymphoma." (PMID 25823848, 2015). "We investigated tumor expression levels of histone-modifying enzymes LSD1, HDAC2 and SIRT1 in relation with patient survival and tumor relapse in a retrospective cohort of 460 breast cancer patients." (PMID 25139823, 2014). "Recently, SIRT1 has been shown to be an important target of miR-200 in regulating breast cancer cell migration." (PMID 25424420, 2014). "Our study identified combined expression levels of the histone-modifying enzymes LSD1, HDAC2 and SIRT1 as an independent prognostic factor for patient survival and tumor relapse in breast cancer patients." (PMID 25139823, 2014). "The mechanism of SIRT1 and Notch1 signaling in breast cancer progression needs to be further studied in order to harness the potential of SIRT1and N1IC expression in the clinical setting." (PMID 25420528, 2014). "A reduction in SIRT1 levels was shown to promote the metastasis of breast epithelial cells in an orthotopic model of breast cancer, as well as increase the motility of the epithelial cells." (PMID 25424420, 2014). "The most striking research in our study was the evaluation of correlation between SIRT1 protein and Notch1 signaling with breast cancer prognosis." (PMID 25420528, 2014). "In this study, we examined the expression pattern of SIRT1, N1IC, and Snail protein using immunohistochemical staining in breast cancer samples, and investigated their association with clinicopathological parameters." (PMID 25420528, 2014). "Here, we describe for the first time an important functional link between SIRT1 and FZD7, which has recently been implicated in breast cancer pathogenesis." (PMID 24897117, 2014). "An enhanced SIRT-1 expression has been observed in breast cancer cells treated with secoiridoid polyphenols extracted from extra-virgin olive oil and in the heart of SAMP8 mice fed with a diet enriched with olive oil phenolics." (PMID 25279550, 2014). "Immunohistochemical staining for LSD1, HDAC2 and SIRT1 was performed on tissue microarrays of tumor and corresponding normal formalin-fixed paraffin-embedded tissues from breast cancer patients." (PMID 25139823, 2014). "Our study here showed that dietary resveratrol (sufficient to give a daily dose of 50 mg/kg) had little effect on the development of mammary tumors in either Sirt1+/+ or Sirt1Y/Y mice." (PMID 25380034, 2014). "For example, SIRT1, 4, 5, and 7 have been described as being upregulated in certain cancers, while reduced SIRT1 levels have been reported in breast cancer and hepatic cell carcinoma." (PMID 25486244, 2014). "In lung cancer, the SIRT1 activator compound 1720 was shown to increase lung metastasis of implanted breast cancer cells, suggesting SIRT1 as a potential target for suppressing metastasis to the lung." (PMID 25424420, 2014). "The prognostic impact of SIRT1 expression and Notch1 signaling was also analyzed in 122 of all 150 patients with breast carcinoma (because of the missing survival data in 28 patients)." (PMID 25420528, 2014). "Deleted in breast cancer 1(DBC1) was first identified by its deletion in breast cancer and was suggested as a tumor suppressor because it acts as a suppressor of SIRT1." (PMID 24019980, 2013).
breast cancer (continued). "Increased expression of SIRT1 has been reported in numerous types of cancer in human such as prostate cancer, leukemia, primary colon cancer, and breast cancer." (PMID 24223900, 2013). "In the same vein, BRCA1 enhances sirtuin 1 activity, reducing cell growth and increasing apoptosis in breast cancer cells." (PMID 24127549, 2013). "Activation of SIRT1 significantly promotes tumor cell migration and metastasis of breast cancer in mice." (PMID 24223900, 2013). "It is reported that SIRT1 is increased in many human tumors, such as breast cancer, ovarian cancer, prostate cancer, gastric cancer, colon cancer, diffuse large B-cell lymphoma, acute myeloid leukemia and Bowen’s disease." (PMID 23805287, 2013). "There have been a crosslinking reported between Class III histone deacetylase SIRT1, a proposed oncogene in breast cancer, and miR-200." (PMID 23497588, 2013). "A putative SIRT1 activator was found to promote the formation of lung metastases in a breast cancer xenograft model." (PMID 24278473, 2013). "Up-regulation of SIRT1 has been reported in various human malignancies including prostate cancer, breast cancer, lymphoma, colon cancer, and gastric cancer." (PMID 24223900, 2013). "miR-22 is a tumor suppressor that induces cellular senescence (by targeting CDK6, SIRT1 and Sp1) and is frequently downregulated in ER+ breast cancer." (PMID 24146960, 2013). "Finally, it was observed that SIRT1 overexpression is associated with decreased miR-200a in breast cancer patient samples, indicating that miR-200a may be a potential tumor suppression target in breast cancer metastasis." (PMID 23497588, 2013). "Others have reported SIRT1 overexpression in primary and murine studies of prostate cancer and found a requirement for SIRT1 for pro-survival signalling in oestrogen positive breast cancer, where expression also correlates with poor prognosis." (PMID 24258275, 2013). "We undertook to directly test the idea that the protein deacetylase activity of SIRT1 suppresses tumor formation in mice that develop aggressive mammary carcinomas under the influence of the polyoma middle T oncogene." (PMID 24278473, 2013). "SIRT1 was determined to be an indicator of poor prognostic for gastric carcinoma, hepatocellular carcinoma, breast carcinoma, and diffuse large B cell lymphoma." (PMID 24019980, 2013). "A redundancy mechanism also exists in breast cancer cells whereby silencing of both SIRT1 and SIRT2 is required to induce cell death." (PMID 22768255, 2012). "We tested the effects of SIRT1 on a series of colon and breast cancer phenotypic characteristics that would be predicted to change dramatically with re-expression of the TSGs under study." (PMID 16596166, 2006). "Similarly, both SIRT1 mRNA and protein levels were significantly reduced in breast cancer cells co-cultured with MDSCs." (PMID 41281644, 2025). "Survival analysis of the TCGA BC cohort stratified by SIRT1 mRNA levels revealed that patients with low SIRT1 mRNA levels had shorter overall survival compared to those with high SIRT1 mRNA levels, highlighting the tumor suppressor role of SIRT1 in breast cancer." (PMID 41281644, 2025). "In breast cancer, SIRT1 may act as a tumor suppressor in early stages by maintaining genomic stability but promotes epithelial–mesenchymal transition, metastasis, and chemoresistance in aggressive subtypes such as triple-negative breast cancer." (PMID 41300302, 2025). "SIRT1 expression is significantly reduced in human breast cancer." (PMID 41281644, 2025).